XBP1 (X-box binding protein 1)
Diseases named in the same sentence as XBP1 in open-access papers (continued):
Sharing a sentence is not in itself a finding about the gene and the disease.
depression (8 papers, 2015 to 2025). "We also obtained the result that XBP1 increased the occurrence of psychiatric disorders and depression by Phenome-wide MR Analysis." (PMID 39170695, 2024). "Scientific evidence also suggests that an estrogen β agonist can alleviate ER stress-induced anxiety and depression by preserving the IRE1α/XBP1 pathway." (PMID 34947907, 2021). "With the high expression of XBP1 in blood, it may increase mood disorders (OR = 1.12,95%CI, 1.07–1.18,Pfdr = 0.003),depression (OR = 1.11,95%CI, 1.05–1.17,Pfdr = 0.019) and endocarditis (OR = 1.58,95%CI, 1.29–1.94,Pfdr = 0.003) risk of develop-ment." (PMID 39170695, 2024). "Key measures of the ER stress response, such as BiP (chaperone ER), ER-degradation-enhancing alpha-mannosidase-like protein 1 (EDEM1), CHOP C/EBP homologous protein, and X-box binding protein 1 (XBP1), are significantly elevated in patients with a major depression disorder." (PMID 36430976, 2022). "In the pathophysiology of Major Depressive Disorder (MDD), elevated levels of ER stress markers such as GRP78, CHOP, and XBP1 have been found in both animal models and human subjects with depression." (PMID 41473415, 2025). "Fluoxetine reduced apoptosis and catalepsy and improved movement by decreasing GRP78, XBP1, CHOP, and caspase-3 levels in ROT-treated rats, suggesting therapeutic potential for PD patients with depression." (PMID 41416041, 2025). "Increased expression levels of XBP-1 and CHOP in LH rats indicate their possible role in inflammation and subsequent development of depression." (PMID 26793110, 2015). "Furthermore, icariin alleviates neuroinflammation in the hippocampus of mice with depression by inhibiting the high mobility group box-1 (HMGB1)/receptor for advanced glycation end-products (RAGE) signaling pathway and activating the X-box binding protein 1 spliced (XBP1s)/NF-κB signaling pathway." (PMID 38915473, 2024).
ischemia (8 papers, 2010 to 2023). A hypoperfusion of the BLOOD through an organ or tissue caused by a PATHOLOGIC CONSTRICTION or obstruction of its BLOOD VESSELS, or an absence of BLOOD CIRCULATION. "Total XBP1 protein was unchanged in ischemia and showed a trend to decrease 24% after reperfusion (P = 0.094, 95% CI [−52.58, 9.84]) compared to baseline." (PMID 24159375, 2013). "ATF4 mRNA and XBP1 mRNA, which were present in control rats and had increased markedly in the lungs which limbs underwent 4h of ischemia and 4h of reperfusion." (PMID 20148646, 2010). "Our findings point to an overrepresentation of xbp1, a transcription factor that modulates not only the cellular response to endoplasmic reticulum stress, but also vascular endothelial growth factor-induced angiogenesis in adult tissues submitted to ischemia." (PMID 37958681, 2023). "However, expression of XBP1 or Hrd1 is able to prevent cardiac remodeling in hearts of mice subjected to ischemia-reperfusion injury and pressure overload." (PMID 35350536, 2022). "Further detailed investigation will be required to address the crosstalk between XBP1 and HIF-1 in both ECs and SMCs following ischemia." (PMID 27338006, 2016). "The IRE1a-XBP1 pathway is activated in reperfusion only if CIT surpasses 8 h, and IRE1a RNase activation is not detected before reperfusion but rather is only observable when preceded by at least 12 h of ischemia." (PMID 34888321, 2021).
pancreatic adenocarcinoma (8 papers, 2015 to 2023). "Tumor growth and survival was severely compromised by blocking the expression of XBP1 in human pancreatic adenocarcinomas under hypoxic condition." (PMID 26633383, 2015). "To verify the role of UPR receptors in the generation of procoagulant EVs from pancreatic adenocarcinoma cells, we evaluated the effect of X-box binding protein 1 (XBP1) and PERK depletion on EV-mediated thrombin generation using a plasma-based thrombin generation assay." (PMID 37651191, 2023). "However, in a later publication, these authors showed that XBP1 inhibition reduced angiogenesis in a pancreatic adenocarcinoma model, suggesting that the effects of XBP1 on angiogenesis may be cell type dependent." (PMID 26157705, 2015). "Analysis of XBP1 expression between normal and tumour samples from several human cancers using GEPIA (gene expression profiling interactive analysis) showed the higher levels of XBP1 in tumours as compared to normal tissue except in pancreatic adenocarcinoma (SF 1)." (PMID 36997866, 2023).
Stroke (8 papers, 2019 to 2024). Sudden impairment of blood flow to a part of the brain due to occlusion or rupture of an artery to the brain. "Stroke activates O-linked beta-N-acetylglucosamine (O-GlcNAc) modification in the penumbra in neurons of young mice, and XBP1-dependent O-GlcNAc modification was neuroprotective." (PMID 35783104, 2022). "Subsequently, further research evaluated and confirmed that thiamet-G improved stroke outcomes in neuron-specific xbp1-knockout mice, including long-term functional recovery." (PMID 38491477, 2024). "They showed that O-GlcNAcylation was activated in an xbp1-dependent manner in the ischaemic penumbra after stroke, and this activation was impaired in the aged brain." (PMID 38491477, 2024). "After a stroke, O-GlcNAcylation activation in young mouse stroke hemidesmosiderotic neurons is predominantly reliant on xbp1." (PMID 38783961, 2024). "In adult tissues of mice, XBP1 can regulate the proliferation of endothelial cells and angiogenesis after stroke via the VEGF signaling pathway." (PMID 35783104, 2022). "As quantification of the data between publications is difficult, we used the number of publications reporting the expression of MANF or XBP1 at each time point as an indication of gene expression after stroke resulting in an “overexpression confidence”." (PMID 35783104, 2022). "Meanwhile, the activation of endoplasmic reticulum stress-related pathways and the upregulation of XBP1 are key features of the widespread presence of various brain-related diseases, including stroke." (PMID 34737845, 2021). "To determine the activation of the most conserved IRE1α-XBP1 pathway after stroke, we measured spliced Xbp1 mRNA (Xbp1s) and mRNA levels of its downstream target gene Dnajb9 using RT-qPCR and performed an Xbp1s splicing detection assay." (PMID 31683519, 2019). "This research suggests a protective role of the IRE1/XBP1 pathway after stroke." (PMID 37008060, 2023). "In summary, the expression of MANF and XBP1 after stroke has been detected in several time points." (PMID 35783104, 2022). "The primary focus of this review is to highlight the importance of the UPR and IRE1/XBP1 pathway in brain injuries and the potential of MANF as a therapeutic agent in stroke." (PMID 35783104, 2022). "We will focus on comparing the role of XBP1 and MANF in stroke and the function of MANF as a regulator of inflammation and neurogenesis." (PMID 35783104, 2022). "A similar XBP1 expression pattern was accompanied by the activation of other UPR pathways, collectively showing that stroke induces ER stress at the lesion site and penumbra." (PMID 35783104, 2022). "A different research indicates that the IRE1/XBP1 pathway of the UPR becomes active during IS, and the lack of Xbp1 results in deteriorating stroke consequences." (PMID 39640236, 2024). "Stroke induces the activation of IRE1 and the processing of XBP1 mRNA." (PMID 37008060, 2023). "Furthermore, activation of Xbp1 mRNA splicing and post-ischemic shutdown of translation resulting from phosphorylation of eIF2α were evident after cerebral ischemia, implying a major role of the IRE1α and the PERK arm of the UPR in stroke pathology." (PMID 31683519, 2019).
type 2 diabetes (8 papers, 2013 to 2025). "We find that decreased XBP1 expression in pancreatic islet cells is associated with increased type 2 diabetes risk, and that the variants associated with reduced XBP1 expression are more common in East and South Asians as well as African populations." (PMID 40993285, 2025). "The discovery of this association in type 2 diabetes and glycaemic traits in humans highlights the potential for development of strategies to therapeutically enhance XBP1 expression in pancreatic beta-cells to reverse beta-cell decline and dysfunction." (PMID 40993285, 2025). "We performed colocalisation analyses to test whether XBP1 expression in pancreatic islets and type 2 diabetes share causal variants." (PMID 40993285, 2025). "Decreased spliced XBP1 expression was observed in islets of type 2 diabetic patients and studies adopting embryonic deletion of Xbp1 using the rat insulin promoter showed that it is required for optimal beta cell development and proinsulin processing." (PMID 35316840, 2022). "XBP1 expression is reduced in islets of people with type 2 diabetes, but its role in adult differentiated beta cells is unclear." (PMID 35316840, 2022). "One study suggested hippocampal cells adapt to type 2 diabetes-induced prolonged ER stress with partial suppression of X-box-binding protein 1 (XBP1) and glucose regulated protein-78 (GRP78/BiP)." (PMID 24223941, 2013). "Thus, our studies suggest that the decline in spliced XBP1 expression found in type 2 diabetes contributes to the failure of beta cells to secrete sufficient amounts of insulin to meet metabolic demand." (PMID 35316840, 2022). "From a therapeutic perspective, targeting XBP1 might help to reverse the process of beta cell dedifferentiation and restore functional beta cell mass in type 2 diabetes." (PMID 35316840, 2022). "A PCA plot bar graph based on the expression levels of MAFA, NKX6.1, CCT4, XBP1 and GRP78, as well as PDIA1, shows a clearer division between the three groups, highlighting the progression from NGT to IGT and then type 2 diabetes." (PMID 36280617, 2023). "In the present study, the increases of Bip transcription, eIF2α phosphorylation, XBP-1 mRNA splicing and CHOP expression was observed in the liver of type 2 diabetic rats." (PMID 24918756, 2014). "In the present study, the levels of Bip mRNA, eIF-2α phosphorylation, XBP-1 mRNA splicing and CHOP expression were significantly elevated in the liver of type 2 diabetic rats compared to control rats (P<0.05 or 0.01)." (PMID 24918756, 2014).
acute myeloid leukemia (7 papers, 2016 to 2025). Acute myeloid leukemia (AML) is a group of neoplasms arising from precursor cells committed to the myeloid cell-line differentiation. "The cytotoxicity of MKC-3946 toward acute myeloid leukemia cells was also associated with the blockade of XBP1 mRNA splicing." (PMID 40650182, 2025). "On the other hand, increased levels of mature and spliced XBP1 forms were associated with better overall survival of patients with acute myeloid leukemia (AML)." (PMID 40650182, 2025). "Intriguingly, Chemotherapy can activate endoplasmic reticulum stress to produce ICD by regulating the expression of intracellular XBP1 in multiple cancers (eg., melanoma, colorectal carcinoma, and acute myeloid leukemia)." (PMID 35991556, 2022). "Moreover, in acute myeloid leukemia JUN was recently found to be involved in the transcription of the UPR transcription factors XBP1 and ATF4." (PMID 29423023, 2018). "Here, we show that the expression of both mature and spliced forms of XBP1 (XBP1s) is up-regulated in acute myeloid leukemia (AML) cell lines and AML patient samples." (PMID 26934650, 2016). "In acute myeloid leukemia (AML), chemotherapeutic stress activates UPR transcription factors (e.g., XBP1 and ATF4), while lysosomal adaptation supports survival and ROS enhances genomic instability." (PMID 40723802, 2025). "In acute myeloid leukemia (AML) cell lines and patient samples, either STF-083010 or HNA attenuated XBP1 mRNA splicing and evoked a cytotoxic effect." (PMID 33562589, 2021).
chronic lymphocytic leukemia (7 papers, 2014 to 2025). "The T‐cell leukaemia/lymphoma 1 (TCL1) oncoprotein has been observed to interact with XBP1 in chronic lymphocytic leukemia (CLL), and the inhibition of XBP1s expression resultes in a reduction in the progression of CLL." (PMID 39188936, 2024). "In chronic lymphocytic leukemia (CLL), malignant cells exploit the IRE1α-XBP1 pathway to overproduce secretory immunoglobulin M (sIgM), driving myeloid-derived suppressor cells (MDSCs) accumulation and enhancing their immunosuppressive activity." (PMID 41209558, 2025).
diabetic retinopathy (7 papers, 2014 to 2026). "Given that cell injury and cell death of retinal neurons results in irreversible vision loss, the ability of XBP1 to mitigate ER stress in retinal cells under chronic disease conditions such as diabetic retinopathy is, therefore, of significant interest." (PMID 31242599, 2019). "Thus, diabetic XBP1 cKO mice experience a loss of RGCs at an earlier stage of diabetic retinopathy than WT mice." (PMID 31242599, 2019). "The exosomal lncRNA SNHG7 derived from MSC also exerted inhibitory effects on EndoMT and vessels generation in diabetic retinopathy through mir34a-5p/XBP1 pathway." (PMID 38789630, 2024). "The exact function and implication of XBP1 in the pathogenesis of diabetic retinopathy remain elusive." (PMID 25530974, 2014). "Focusing on this less studied pathway, we summarize recent progress in studies of the UPR pertaining to diabetic changes in retinal vasculature and neurons, highlighting the perspective of XBP1 as a potential therapeutic target in diabetic retinopathy." (PMID 25530974, 2014). "In retinal endothelial cells in diabetic retinopathy, hyperlipidaemia induces proinflammatory responses by activating the STING pathway via IRE1α-XBP1." (PMID 38129863, 2023). "By targeting the miR-3aa-5p/XBP1 axis, sEV lncRNA SNHG7 inhibits high glucose induced endothelial mesenchymal transition and tube formation and impairs the pathogenesis of diabetic retinopathy." (PMID 36057662, 2022).
Hypocholesterolemia (7 papers, 2017 to 2024). An decreased concentration of cholesterol in the blood. "Interestingly, either the deletion of XBP1 or the disruption of regulated IRE1-dependent decay (RIDD) can reverse the hypocholesterolemia observed in mice XBP1-deficient mice." (PMID 38025713, 2023). "Inducible deletion of XBP-1 in the adult liver results in hypocholesterolemia and hypotriglyceridemia, as well as a decreased production of lipids in the liver." (PMID 28278289, 2017). "Furthermore, inducible liver-specific deletion of XBP1 resulted in marked hypocholesterolemia and hypotriglyceridemia due to decreased hepatic lipid production." (PMID 39125345, 2024). "Similarly, XBP1 modulates lipid metabolism since selective deletion of Xbp1 in the liver results in hypocholesterolemia and hypotriglyceridemia, together with modulation of lipogenic genes indicating that XBP1 is a regulator of lipogenesis." (PMID 36341413, 2022). "Mice lacking XBP1 in the liver exhibit severe hypotriglyceridemia and hypocholesterolemia due to reduced lipogenesis, further demonstrating the importance of the IRE1/XBP1 branch in fatty acid synthesis." (PMID 38638434, 2024). "The absence of the XBP1 triggers the activation of IRE1α, diminishing the degradation of downstream mRNAs related to lipid metabolism and inducing noticeable hypocholesterolemia in mice." (PMID 38025713, 2023).
prion disease (7 papers, 2011 to 2020). A transmissible disease that is caused by a protein that is able to induce abnormal folding of normal cellular proteins, leading to characteristic spongiform brain changes, which are associated with neuronal loss without an inflammatory response. "In a cellular model of prion disease, XBP1s overexpression prevented PrP misfolding, whereas a dominant negative form of XBP1 and IRE1α significantly increased PrP aggregation." (PMID 32854418, 2020). "Surprisingly, the UPR response regulator X-box-binding protein-1 (XBP-1) has no detectable role in the progression of prion disease and prion propagation in experimental animals." (PMID 33234071, 2020). "The inability of PrP106–126 to induce XBP1 splicing agrees with the observation that elimination of XBP1 in mice did not alter the course of prion disease, suggesting that XBP1 plays no physiological role in prion diseases." (PMID 22528838, 2012). "The neuroprotective activity of XBP1 in prion diseases was tested in mice lacking XBP1 in the brain; these animals showed normal prion replication and neuropathology, suggesting that other UPR pathways may compensate the absence of XBP1." (PMID 32854418, 2020). "Regardless of the precise mechanism by which PrPSc stimulates ER stress, the fact that genetic ablation of XBP1 or caspase-12 does not modify the onset or progression of symptoms in prion-infected mice indicates that this pathway is not essential for prion diseases acquired by infection." (PMID 21559407, 2011). "This suggests that the IRE-1/XBP-1 UPR branch, which is activated in human prion diseases as demonstrated in the present work, may not contribute to the occurrence of prion pathology." (PMID 28449707, 2017).
retinal degeneration (7 papers, 2012 to 2025). Degeneration of the retina. "The molecular mechanisms behind the retinal degeneration in XBP1 cKO mice, possibly including dysregulation of synaptic proteins and synapse formation, increased neuronal cell death, and disruption of cellular metabolism, are currently being investigated." (PMID 31242599, 2019). "The defensive role of XBP1 was also investigated in a study of the Drosophila model of retinal degeneration, which found that decreased Xbp1 gene dosage accelerated retinal degeneration in adRP retinas." (PMID 24068865, 2013). "Our results show that in a rat model of light-induced retinal degeneration, XBP1 activation was suppressed in the RPE/choroid complex, accompanied by decreased anti-oxidant genes and increased oxidative stress." (PMID 22715395, 2012). "Our data suggest that age-related neurodegeneration occurs at an accelerated pace in the retina lacking XBP1 thus indicating a critical role of XBP1 in regulation of age-related retinal degeneration." (PMID 29615095, 2018). "Our results demonstrate that XBP1 activation in the RPE was suppressed by light stress, in parallel with decreased expression of ER chaperone and anti-oxidant genes, in a rodent model of retinal degeneration." (PMID 22715395, 2012).
rheumatoid arthritis (7 papers, 2014 to 2024). A chronic, systemic autoimmune disorder characterized by inflammation in the synovial membranes and articular surfaces. "Elevated IRE1α signaling, as determined by increased XBP1 splicing, has been reported in monocytes obtained from rheumatoid arthritis and tumor necrosis factor receptor associated periodic syndrome patients." (PMID 31417078, 2019). "Moreover, a feedback loop of TNF-α-induced XBP1 in rheumatoid arthritis synoviocytes has been observed." (PMID 36421428, 2022). "They showed that TLR-dependent XBP1 activation is operative in the synovial fibroblasts (SF) of active rheumatoid arthritis (RA) patients." (PMID 26417435, 2015). "While XBP-1 was upregulated in synovial fibroblasts of Rheumatoid Arthritis (RA) patients, other UPR markers were largely down-regulated, suggesting the uncoupling between the two signaling pathways." (PMID 25216759, 2014).